GSTO2 (glutathione S-transferase omega 2)
Diseases named in the same sentence as GSTO2 in open-access papers (continued):
Sharing a sentence is not in itself a finding about the gene and the disease.
Colon Cancer (1 paper, 2023). "Univariate and multivariate Cox regression analyses showed that GSTO2 was an independent risk factor for poor prognosis in colon cancer." (PMID 36688005, 2023). "Our research shows that Glutathione S-transferase omega 2 is overexpressed in colon cancer patients, and this overexpression is associated with a poor prognosis." (PMID 36688005, 2023). "Then, the overall survival analysis of those cancers indicated that GSTO2 expression at a high level in colon cancer patients had an association with a poor prognosis." (PMID 36688005, 2023). "Univariate and multivariate Cox regression analyses showed that Glutathione S-transferase omega 2 was an independent risk factor for poor prognosis in colon cancer." (PMID 36688005, 2023). "Second, while we verified GSTO2 as a risk factor for colon cancer through in vitro experiments, the direct mechanism of GSTO2's involvement in the occurrence and development of colon cancer remains unclear." (PMID 36688005, 2023). "Although we verified GSTO2 as a risk factor for colon cancer through in vitro experiments, the direct mechanism of GSTO2's involvement in the occurrence and development of colon cancer remains unclear." (PMID 36688005, 2023). "This indicates that GSTO2 is highly expressed in colon cancer and is associated with poor survival." (PMID 36688005, 2023). "The Kaplan–Meier OS analysis indicated that GSTO2 is a risk factor for colon cancer patients." (PMID 36688005, 2023). "A Wilcoxon rank-sum test showed that GSTO2 expression was significantly higher in colon cancer than in adjacent tissues (p = 4.23 × 10−5)." (PMID 36688005, 2023). "We performed univariate Cox regression and found that age, stage, T, M, N, and GSTO2 are the factors that affect the prognosis of colon cancer." (PMID 36688005, 2023). "In summary, we found that Glutathione S-transferase omega 2 can be used as a molecular indicator of colon cancer prognosis." (PMID 36688005, 2023). "Then, as the results show, we found that GSTO2 expression in colon cancer tissues was higher than in normal colon tissues at the mRNA level.Next, we used the HPA database to explore GSTO2's protein level." (PMID 36688005, 2023). "The results showed that GSTO2 expression levels can affect the immune microenvironment of colon cancer cells." (PMID 36688005, 2023). "We performed a CCK8 assay and an EdU assay to verify the effect of GSTO2 on the proliferative ability of colon cancer." (PMID 36688005, 2023). "Our study found that GSTO2 expression levels can affect the immune microenvironment of colon cancer cells." (PMID 36688005, 2023). "Herein, our study aimed to investigate the exact role of Glutathione S-transferase omega 2 in colon cancer." (PMID 36688005, 2023). "The high expression of Glutathione S-transferase omega 2 is significantly correlated stage with stage, M, and N classification progression in colon cancer by statistical analysis." (PMID 36688005, 2023). "We analyzed the difference in GSTO2 expression levels between colon cancer and normal tissues and plotted them in scatter plots." (PMID 36688005, 2023). "In vitro, gene silencing of Glutathione S-transferase omega 2 inhibited colon cancer cells' growth and migration." (PMID 36688005, 2023). "The results showed that GSTO2 protein expression was significantly higher in colon cancer than in adjacent tissues (p = 0.0016)." (PMID 36688005, 2023). "To analyze the value of GSTO2 in the occurrence and development of COAD, we studied the relationship between GSTO2 and some colon cancer molecular markers through the TIMER database." (PMID 36688005, 2023). "Subsequently, we further explored the relationship between GSTO2 expression levels and colon cancer." (PMID 36688005, 2023). "To determine the effect of GSTO2 expression level on the migration ability of colon cancer cells, we performed wound healing and transwell migration experiments." (PMID 36688005, 2023).
Colon Cancer (continued). "In addition, we also found that Glutathione S-transferase omega 2 expression levels can affect the immune microenvironment of colon cancer cells." (PMID 36688005, 2023). "In addition, western blot and immunohistochemistry were performed to evaluate the protein levels of Glutathione S-transferase omega 2 in colon cancer tissues." (PMID 36688005, 2023). "Also, multivariate Cox regression analysis showed that T, age, and GSTO2 are the factors that affect the prognosis of colon cancer." (PMID 36688005, 2023). "In addition, our results showed that gene silencing of GSTO2 significantly inhibited colon cancer cell growth and migration." (PMID 36688005, 2023). "So, we will continue to explore the role of GSTO2 in colon cancer in the future." (PMID 36688005, 2023). "In addition, clinical relevance based on the TGCA Database showed that the overexpression of GSTO2 in colon cancer tissues is related to M classification, N classification, and stage, with a poor overall survival rate." (PMID 36688005, 2023). "Finally, due to the importance of the tumor microenvironment in tumor development, we discussed the correlation between GSTO2 expression and colon cancer immune cell invasion." (PMID 36688005, 2023). "The results (p = 5.145 × 10−9) showed that the expression level of GSTO2 in colon cancer tissues was much higher than that in normal colon tissues, and statistical analysis of the different results was completed by R. Next, 41 pairs of the 514 samples were analyzed for pairwise differences." (PMID 36688005, 2023). "So, we concluded that the differential genes of GSTO2 may promote colon cancer progression via the PI3K-Akt signaling pathway." (PMID 36688005, 2023). "However, the relationship between GSTO2 and colon cancer has rarely been studied." (PMID 36688005, 2023). "Similarly, IHC results also showed that the GSTO2 protein was highly expressed in colon cancer." (PMID 36688005, 2023). "Therefore, we believe that GSTO2 has a high expression level in colon cancer." (PMID 36688005, 2023). "However, the role of Glutathione S-transferase omega 2 in the development of colon cancer remains unclear." (PMID 36688005, 2023). "The enrichment analysis of GO and KEGG showed that the high expression of GSTO2 is related to the ECM receptor interaction and may promote colon cancer progression via the PI3K-Akt signaling pathway." (PMID 36688005, 2023).
colorectal cancer (1 paper, 2025). A primary or metastatic malignant neoplasm that affects the colon or rectum. "Here, subjects with the homozygous wild-type GSTO2*N142 genotype (N/N) and with a positive family history were found to be at a high risk for developing colorectal cancer, when compared to subjects with other genotypes (i.e., D/D or N/D) and a negative family history of cancer." (PMID 40724836, 2025).
diabetic nephropathy (1 paper, 2023). "Namely, we observed that individuals with the GSTO2*AG genotype were 2.6-fold more prone for symptomatic diabetic nephropathy development (OR = 2.59, 95%CI = 1.11–6.05, p = 0.028) in comparison to the carriers of the wild-type GSTO2*AA genotype." (PMID 36676788, 2023). "The present study was designed to investigate the possible modifying effect of glutathione transferase polymorphisms (GSTM1, GSTT1, GSTP1 rs1138272/rs1695, GSTO1 rs4925 and GSTO2 rs156697) in the susceptibility to T2DM and diabetic nephropathy." (PMID 36676788, 2023). "In our study, we found that individuals with the GSTO2*AG genotype were more prone to symptomatic diabetic nephropathy development in comparison to the carriers of the wild-type GSTO2*AA genotype." (PMID 36676788, 2023). "Hence, the present study was designed to investigate the possible modifying effect of GSTs polymorphisms (GSTM1, GSTT1, GSTP1, GSTO1 and GSTO2) in the susceptibility to T2DM and diabetic nephropathy as its major microvascular complication." (PMID 36676788, 2023).
gastric atrophy (1 paper, 2025). "On the other hand, carriers of at least one GSTO2*G variant allele had decreased odds of developing gastric atrophy (OR = 0.39, 95%CI = 0.16–0.94, p = 0.04) and active inflammation (OR = 0.11, 95%CI = 0.02–0.64, p = 0.013) than GSTO2*A reference carriers." (PMID 39859205, 2025).
gastric cancer (1 paper, 2025). A primary or metastatic malignant neoplasm involving the stomach. "On the other hand—when compared to the other two genotypes (i.e., N/N, N/D)—the homozygous GSTO2*N142D (D/D) genotype was found to be associated with a lower risk of gastric cancer in subjects without a history of cancer in their first-degree relatives." (PMID 40724836, 2025).
gastritis (1 paper, 2025). Inflammation of the stomach. "According to our analysis, the GSTO1 and GSTO2 polymorphisms did not exhibit any influence on the risk of HP-positive gastritis development." (PMID 39859205, 2025). "According to our analysis, the GSTO1 rs4925and GSTO2 rs156697 polymorphisms did not exhibit any influence on the risk of HP-positive gastritis development." (PMID 39859205, 2025).
glaucoma (1 paper, 2021). Increased pressure in the eyeball due to obstruction of the outflow of aqueous humor. "The presented results revealed that there was a significant association between the ND genotype of GSTO2 and the pathogenesis of glaucoma." (PMID 34858663, 2021). "In conclusion, the represented results showed that the ND genotype of GSTO2 could be considered as a genetic risk factor for the development of glaucoma." (PMID 34858663, 2021). "Our results demonstrated that the ND genotype of GSTO2 could be considered as a genetic risk factor for the development of glaucoma, especially in males." (PMID 34858663, 2021). "Evidence from this study showed that genotype GSTO2 (142N > D) has a significant association with the pathogenesis of glaucoma in southern Iran, which can be an important finding in predicting the pattern of the disease and preventive care in people with this genotype." (PMID 34858663, 2021). "The present study evaluated the association of GSTO2 (142N > D) and TGF-β1 (869T > C) polymorphisms with glaucoma of two common types (POAG and CACG)." (PMID 34858663, 2021). "The present study is valuable in that there are no reports of an association between TGF-β 869T > C and GSTO2 (142N > D) with glaucoma." (PMID 34858663, 2021). "Since previous studies have highlighted the importance of the association of GSTO2 and TGF-β1 genes with the pathogenesis of glaucoma, this study aimed to survey the association of two important previously overlooked polymorphisms of these genes with two common types of glaucoma." (PMID 34858663, 2021).
glioblastoma (1 paper, 2025). The most malignant astrocytic tumor (WHO grade IV). "The expression levels of RELN and GSTO2 were significantly lower in glioblastoma samples compared to controls." (PMID 40171042, 2025). "These pathways, which are linked to tumor progression, underscore the potential roles of RELN and GSTO2 in glioblastoma biology." (PMID 40171042, 2025). "By intersecting the results of these methods, two genes, RELN and GSTO2, emerged as shared biomarkers between glioblastoma and degenerative CNS diseases." (PMID 40171042, 2025). "Similarly, expression levels of RELN and GSTO2 significantly decreased glioblastoma samples compared to controls." (PMID 40171042, 2025). "The relationship between these pathways and hub gene expression is further depicted in a heatmap for intuitive visualization, supporting the hypothesis that RELN and GSTO2 are critical mediators at the intersection of glioblastoma and degenerative CNS disease mechanisms." (PMID 40171042, 2025).
head and neck squamous cell carcinoma (1 paper, 2025). A squamous cell carcinoma that arises from any of the following anatomic sites: lip and oral cavity, nasal cavity, paranasal sinuses, pharynx, larynx, and salivary glands. "Considering the role of GSTs in detoxification, a study on Thai subjects focused on GSTO1*A140D and GSTO2*N142D polymorphisms in head and neck squamous cell carcinoma (HNSCC) risk." (PMID 40724836, 2025).
hemorrhagic stroke (1 paper, 2024). A stroke caused by a bleed on the brain. "This suggests that Gsto2 plays a pivotal role in ferroptotic neuronal injury following hemorrhagic stroke." (PMID 38386166, 2024). "Additionally, we observed a decrease in Gsto2 expression both in vitro and in vivo after hemorrhagic stroke." (PMID 38386166, 2024). "The decreased expression of GSTO2 in the glutathione metabolic process may be involved in ferroptotic neuronal injury following hemorrhagic stroke." (PMID 38386166, 2024). "To investigate whether Gsto2 is involved in ferroptotic neuronal damage after hemorrhagic stroke, we established a hippocampal hemorrhage mouse model (h-ICH)." (PMID 38386166, 2024).
Infertility (1 paper, 2023). "Next, we investigated whether the selected candidates, GSTP1, GSTO2, and GSTK1, played important roles in the observed infertility caused by decreased Klotho expression." (PMID 37759974, 2023). "After analysis of the published dataset (GSE6872,), the mRNA levels of GSTP1, GSTO2, and GSTK1 were remarkably reduced in sperm from infertile men, who had severe sperm morphological defects, compared to sperm from fertile individuals." (PMID 37759974, 2023).
intracerebral hemorrhage (1 paper, 2024). A cerebrovascular disorder characterized by bleeding into one or both cerebral hemispheres including the basal ganglia and the cerebral cortex. "The expression of GSTO2 protein decreased after hemin treatment in a mouse model of hippocampus-intracerebral hemorrhage, indicating that GSTO2 plays an important role in the adaptive response to ferroptosis." (PMID 38386166, 2024). "Further, we determined the expression of GSTO2 in hemin-treated hippocampal neurons and in a mouse model of hippocampus-intracerebral hemorrhage (h-ICH) by using Western blot." (PMID 38386166, 2024). "In addition, the expression of GSTO2 was also decreased in a mouse model of hippocampus-intracerebral hemorrhage (h-ICH)." (PMID 38386166, 2024).
melanoma (1 paper, 2024). A malignant, usually aggressive tumor composed of atypical, neoplastic melanocytes. "Genes in cluster 8 (GSTO2, LRRC34), 9 (CLPTM1L) and 10 (CTSS, SETDB1, ANXA9, GOLPH3L, HORMAD1, PPIL3, CASP9, ALS2CR12) underlie the association between melanoma and cancers." (PMID 38308491, 2024).
psoriasis (1 paper, 2025). An autoimmune condition characterized by red, well-delineated plaques with silvery scales that are usually on the extensor surfaces and scalp. "This function of GSTO2 aligns with research findings indicating that ascorbic acid alleviates symptoms associated with skin lesions in psoriasis." (PMID 40278165, 2025).
seminoma (1 paper, 2023). A radiosensitive malignant germ cell tumor found in the testis (especially undescended), and extragonadal sites (anterior mediastinum and pineal gland). "Indeed, the carriers of the GSTO2*G allele (rs156697) were in particular at higher risk of developing seminoma compared to the carriers of GSTO2*AA genotype." (PMID 37374052, 2023). "Due to the biological origin and the clinically distinctive characteristics of the two large categories of testicular GCT, the individual effect of GSTO1*C419A (rs4925), GSTO2*A424G (rs156697), and GSTO2*A183G (rs2297235) polymorphisms on the risk for seminoma development was estimated as well." (PMID 37374052, 2023). "As far as GSTO2rs2297235 polymorphism is concerned, we found that the carriers of the GSTO2*A/G*G/G genotype exhibited increased risk for testicular GCT and seminoma development, as opposed to those with the GSTO2*AA genotype." (PMID 37374052, 2023).
squamous skin cell carcinoma (1 paper, 2024). "GSTO2 functions as a tumor suppressor through p38-mediated MAPK signaling in esophageal and squamous skin cell carcinoma." (PMID 38751776, 2024).
urothelial carcinoma (1 paper, 2025). A malignant neoplasm derived from the transitional epithelium of the urinary tract (urinary bladder, ureter, urethra, or renal pelvis). "On the other hand, the analysis of the haplotypes/diplotypes of GSTO1 and GSTO2 revealed that the diplotype combining GSTO1*C419/GSTO2*A183/GSTO2*G424 had a significantly higher risk of urothelial carcinoma, as compared with other diplotypes." (PMID 40724836, 2025).
cancer (16 papers, 2011 to 2025). A tumor composed of atypical neoplastic, often pleomorphic cells that invade other tissues. "The analysis revealed that subjects with combined variant GSTO1*A/A (GSTO1*A140D; D/D) and GSTO2*G/G (GSTO2*N142D; D/D) genotypes had a higher risk of developing cancer." (PMID 40724836, 2025). "Recent studies have demonstrated two SNPs in GSTO gene [GSTO1 (rs4925: C>A) and GSTO2 (rs156697: A>G)] being associated with different cancer types, and majority of these studies have substantiated GSTO2 as a risk factor for various solid tumors." (PMID 34722260, 2021). "Several studies have discussed the association of GSTO2 with cancers." (PMID 40171042, 2025). "Only a few studies have investigated GSTO2 polymorphisms in non-malignant diseases." (PMID 36676788, 2023). "About 30 patients for all the types of cancer were recruited, and the rates of GSTO1*A140D (rs4925) and GSTO2*N142D (rs156697) polymorphisms were evaluated." (PMID 40724836, 2025). "We used RNA sequencing data from The Cancer Genome Atlas and the Genotype-Tissue Expression database to analyze Glutathione S-transferase omega 2 expressions." (PMID 36688005, 2023). "Moreover, subjects with the GSTO AGG/AGG diplotype of GSTO1*A140D (C419A), GSTO2 5′UTR (-183) A/G, and GSTO2*N142D (A424G) had a 34-fold higher cancer risk when exposed to high levels of arsenic." (PMID 40724836, 2025). "Conversely, reducing GSTO2 activity or expression could increase oxidative stress, promoting cancer cell death, and potentially serving as a therapeutic strategy." (PMID 40171042, 2025). "Furthermore, we plotted a table to show the correlation between GSTO2 mRNA expression levels and various cancer types." (PMID 36688005, 2023). "Diplotype analysis showed that among subjects exposed to high levels of arsenic, the AGG/AGG variant of GSTO1 Ala140Asp, GSTO2 5'UTR (-183)A/G, and GSTO2 Asn142Asp was associated with an increased cancer risk (HRs, 4.91, 95% CI, 1.02-23.74) when compared to the all-wildtype reference, respectively." (PMID 21798077, 2011). "The association of GSTO2 polymorphism with human cancers, such as hepatocellular carcinoma, colorectal and ovarian cancer has been demonstrated but it appears not to be significantly associated with cancer risk." (PMID 26354850, 2015). "GSTO2 and MT1M have been described as tumor suppressors in cancer, and SMAD4 is listed as a tumor suppressor gene in the COSMIC Cancer Gene Census." (PMID 38751776, 2024). "For instance, GSTO2 and PGF were down-regulated while CSF1R, DDB2, HMOX1 and PGFB were up-regulated in both cancers." (PMID 38790250, 2024). "We found the expression of GSTO2 was the lowest in the DLBC, THYM, READ, and COAD para-carcinoma tissues." (PMID 36688005, 2023). "Genes such are GSTA4, GSTO2, KLK3, PGF were down-regulated and E2F2, MMP9, PIM2, VEGFC are up-regulated in all cancer nodules." (PMID 34209090, 2021). "Unfortunately, there are no literature data on GSTO2 expression in cancer, as yet." (PMID 31861116, 2019).